SUMF1 (sulfatase modifying factor 1)
Description:
Oxidase that catalyzes the conversion of cysteine to 3-oxoalanine on target proteins, using molecular oxygen and an unidentified reducing agent. 3-oxoalanine modification, which is also named formylglycine (fGly), occurs in the maturation of arylsulfatases and some alkaline phosphatases that use the hydrated form of 3-oxoalanine as a catalytic nucleophile. Known substrates include GALNS, ARSA, STS and ARSE.
Synonyms: FGE; UNQ3037; LOC100130207; AAPA3037
Tractability: Small molecule: a structure with a bound ligand is known; it has a high-quality binding pocket. Antibody: UniProt predicts a signal peptide or a membrane-spanning region. PROTAC: ubiquitination databases record sites on it; its protein half-life has been measured.
Gene: Protein-coding gene on chromosome 3 (3,700,814 to 4,467,273, reverse strand). Ensembl gene ENSG00000144455.
Subcellular location: Endoplasmic reticulum lumen
Pathways (Reactome):
Metabolism: Glycosphingolipid catabolism
Metabolism of proteins: The activation of arylsulfatases
Gene Ontology:
Molecular function: cupric ion binding; formylglycine-generating oxidase activity; identical protein binding; protein binding; oxidoreductase activity
Biological process: post-translational protein modification; protein oxidation; glycosphingolipid catabolic process
Cellular component: endoplasmic reticulum; endoplasmic reticulum lumen
Genetic constraint (gnomAD): Loss-of-function variants: 48 observed, 48.67 expected, observed/expected ratio (o/e) 0.99, 90% interval 0.78 to 1.25. The synonymous counts are far from expectation, so gnomAD's model fits this gene poorly and the ratio says little. Missense variants: 571 observed, 487.8 expected, observed/expected ratio (o/e) 1.17, 90% interval 1.09 to 1.25. Synonymous variants: 230 observed, 187.03 expected, observed/expected ratio (o/e) 1.23, 90% interval 1.1 to 1.37.
Gene-disease validity (ClinGen):
ClinGen rates the evidence that SUMF1 causes each of these diseases.
mucosulfatidosis (autosomal recessive): Definitive.
Homologues: Orthologues: chimpanzee SUMF1 (99% identical), macaque SUMF1 (96% identical), dog SUMF1 (90% identical), rabbit SUMF1 (89% identical), pig SUMF1 (87% identical), rat Sumf1 (86% identical), mouse Sumf1 (85% identical), guinea pig SUMF1 (68% identical), tropical clawed frog sumf1 (64% identical), zebrafish sumf1 (49% identical), Drosophila melanogaster CG7049 (47% identical). Paralogues in human: SUMF2 (38% identical).
Diseases named in the same sentence as SUMF1 in open-access papers:
SUMF1 is named in the same sentence as 48 diseases in open-access papers, as found by Europe PMC text mining. Sharing a sentence is not in itself a finding about the gene and the disease. The quoted sentences say what the papers report.
Multiple sulfatase deficiency (36 papers, 2013 to 2025). "Biallelic variants in SUMF1 are associated with multiple sulfatase deficiency (MSD), a rare lysosomal storage disorder typically diagnosed in early infancy or childhood, marked by severe neurodegeneration and early mortality." (PMID 38863195, 2024). "Individuals with impaired SUMF1 activity experience an accumulation of sulfated GAGs, resulting in multiple sulfatase deficiency, a disorder characterized by lysosomal storage issues." (PMID 38540990, 2024). "Multiple sulfatase deficiency (MSD) is an extremely rare autosomal recessively inherited disease with a prevalence of 1:500.000 caused by mutations on the sulfatase-modifying-Factor 1 gene (SUMF1)." (PMID 36980153, 2023). "Multiple Sulfatase Deficiency (MIM 272200) is a deficiency due to a post-translation modifier enzyme encoded by the SUMF1 gene (Sulfatase Modifying Factor 1)." (PMID 36672721, 2023). "For example, specific deletion of Sumf1, the gene associated with multiple sulfatase deficiency, in astrocytes induced degeneration of cortical neurons in vivo and in vitro." (PMID 35921286, 2022). "Multiple sulfatase deficiency is an autosomal recessive disorder caused by formylglycine-generating enzyme deficiency due to SUMF1 defects." (PMID 34055681, 2021). "Further demyelinating neuropathies, in detail lysosomal storage diseases [metachromatic leukodystrophy (MLD), globoid cell leukodystrophy (Morbus Krabbe), and multiple sulfatase deficiency (SUMF1 gene)] also showed multifocal nerve enlargement." (PMID 32411079, 2020). "Multiple sulfatase deficiency (MSD) is an ultra‐rare congenital disorder caused by SUMF1 dysfunction and often misdiagnosed due to its complex clinical presentation." (PMID 32048457, 2020). "If only I2S activity is low, genetic testing for MPS II should be performed; if there is a multiple sulfatase deficiency, the SUMF1 gene should be sequenced to confirm multiple sulfatase deficiency (MSD)." (PMID 30442156, 2018). "Mutations in SUMF1 cause multiple sulfatase deficiency, a rare and fatal autosomal recessive disorder characterized by absent activity of all sulfatase enzymes (see Section V.A)." (PMID 26213785, 2015). "Multiple sulfatase deficiency is a rare inherited metabolic disorder caused by mutations in the SUMF1 gene." (PMID 25885655, 2015). "Knocking down of miR-95 in cells isolated from patients with a severe lysosomal storage disorder called multiple sulfatase deficiency due to hypomorphic SUMF1 mutations can increase SUMF1 protein levels, suggesting a potential therapeutic intervention for this disease." (PMID 26579118, 2015). "Biallelic variants in SUMF1 lead to multiple sulfatase deficiency (MSD, MIM #272200), an extremely rare autosomal recessive multisystem lysosomal storage disorder (LSD), with only approximately 150 affected individuals reported to date." (PMID 38863195, 2024). "Multiple Sulfatase Deficiency (MSD) is a rare genetic disorder affecting multiple enzymes (e.g., SUMF1), leading to symptoms that include developmental delay and skeletal abnormalities." (PMID 38540351, 2024). "Multiple sulfatase deficiency (MSD) is a rare lysosomal storage disorder caused due to pathogenic variants in the SUMF1 gene." (PMID 36959582, 2023). "The AR multiple sulfatase deficiency (MSD) is caused by mutations in the SUMF1 gene (sulfatase-modifying factor 1) resulting in tissue accumulation of sulfatides, sulfated glycosaminoglycans, sphingolipids, and steroid sulfates." (PMID 38835422, 2023). "Mutations of the sulfatase modifying factor (SUMF)-1 gene result in the disorder multiple sulfatase deficiency (MSD), since the family of eukaryotic sulfatase enzymes requires post-translational modification for activity." (PMID 36361933, 2022). "Multiple sulfatase deficiency (MSD) is a lysosomal storage disease caused by a deficiency of formylglycine‐generating enzyme due to SUMF1 defects." (PMID 33728250, 2021).
Multiple sulfatase deficiency (continued). "These enzymes are essential for the catabolism of glycosaminoglycans and are deficient in multiple sulfatase deficiency (MSD), as a consequence of mutations in SUMF1 gene." (PMID 27708618, 2016). "Patients 3 and 4 are considered as Multiple Sulfatases Deficiency (MSD) patients as mutations in IDS and SUMF1 are related to this disease." (PMID 39194544, 2024). "For example, it has been shown that astrocytic-specific deletion of Sulfatase Modifying Factor 1 (SUMF1) (Sumf1flox/flox; GFAP-Cre) was sufficient to induce neuron loss in a mouse model of multiple sulfatase deficiency (MSD)." (PMID 35444603, 2022). "Combined impairment of all sulfatases, multiple sulfatase deficiency (MSD), are clinically heterogeneous disorders caused by mutations in SUMF1 or SUMF2." (PMID 33917579, 2021). "Multiple sulfatase deficiency (MSD, MIM #272200) is an ultrarare congenital disorder caused by SUMF1 mutation and often misdiagnosed due to its complex clinical presentation." (PMID 32048457, 2020). "Multiple sulfatase deficiency (MSD), a severe type of LSDs, is caused by defective posttranslational activation of sulfatase-modifying factor 1 and simultaneous deficiency of all sulfatases, leading to accumulation of glysosaminoglycans (GAGs) and aberrant autophagy." (PMID 33292395, 2020). "Recently, using a conditional Cre-mediated deletion of the sulfatase-modifying factor 1 gene (Sumf1), which causes the LSD mucosulfatidosis, researchers were able to demonstrate that SUMF1-deficient astrocytes failed to support function and survival of neurons in a wild-type mouse." (PMID 23907005, 2013). "Multiple sulfatase deficiency (MSD, MIM #272200) results from pathogenic variants in the SUMF1 gene that impair proper function of the formylglycine‐generating enzyme (FGE)." (PMID 36789546, 2023). "Multiple sulfatase deficiency (MSD) is a rare inherited metabolic disorder caused by a deficiency in the formylglycine-generating enzyme (FGE), due to mutations in the sulfatase modifying factor 1 (SUMF1) gene on Chr." (PMID 32825639, 2020).
lysosomal storage disease (11 papers, 2015 to 2025). A metabolic disorder caused by mutations in proteins critical for lysosomal function, including lysosomal enzymes, lysosomal integral membrane proteins, and proteins involved in the post-translational modification and trafficking of lysosomal proteins. "The G237R missense mutation in SUMF1 has been implicated in the pathogenesis of lysosomal storage disease (LSD) in an analysis of the association between a potentially pathogenic variant in 42 LSD and cancer, determining which patients with LSD are at an increased risk of cancer." (PMID 39194544, 2024). "Although it has not been previously linked to PD, mutations in SUMF1 and its sulfatase targets cause a diversity of rare lysosomal storage diseases, many of which have large phenotypic overlap with PD." (PMID 38467937, 2024). "Although SUMF1 and its sulfate esterase targets have not been studied in relation to gout for the time being, mutations in SUMF1 and its sulfate esterase targets lead to a variety of human diseases, especially lysosomal storage diseases." (PMID 39734218, 2024). "SUMF1 is a new player in Menkes disease linking faulty cholesterol biology to the clinical picture and a whole new group of GAG sulfatases, which may lead to mimicry of lysosomal storage disorders." (PMID 33917579, 2021).
breast carcinoma (4 papers, 2010 to 2023). "KM plotter analysis showed improved relapse-free survival with increased expression of PMEPA1, POMT2, VGLL4 and SUMF1 in breast cancer patients indicating their therapeutic potential." (PMID 30760814, 2019). "SUMF1, has been reported whose increased expression could improve relapse‐free survival of breast cancer patients." (PMID 36856182, 2023). "Upon EZH2 knockdown, fold change in the target gene expression for GPNMB, CoL5A1, POMT2, PMEPA1, VGLL4 and SUMF1 was found to be 1.3, 2.8, 2.2, 2, 1.7 and 1.8, respectively in MCF-7 breast carcinoma cells as detected by qPCR." (PMID 30760814, 2019). "A concomitant improved relapse free survival in breast cancer patients with increased expression of POMT2, PMEPA1 and SUMF1 indicated their tumor suppressive behavior." (PMID 30760814, 2019). "Correlating the mRNA expression data, a significantly reduced SUMF1 positive cancer cells was observed in nicotine exposed breast cancer patients when compared to never-smoked patient samples." (PMID 30760814, 2019). "Correlating our previous report, the present study further signifies the finding by demonstrating the abrogated expression of SUMF1 in tissue sections from smoking breast cancer patients in comparison to never-smoked patient samples." (PMID 30760814, 2019). "SUMF1 is located in aUPD regions, which is a common and non-random molecular feature of breast cancer." (PMID 27506935, 2016).
emphysema (4 papers, 2017 to 2024). "SUMF1 deficient mice (Sumf1−/−) developed a lung phenotype similar to the emphysema that is seen in humans." (PMID 30760748, 2019). "Apart from the emphysema-like features, extensive accumulation of GAGs was identified in various cell and tissue types in SUMF1−/− mice." (PMID 38540990, 2024). "The emphysema-like characteristics observed earlier suggested a potential involvement of SUMF1 in the onset of COPD, characterized by emphysema development." (PMID 38540990, 2024). "Sumf1−/− mice exhibited a lung phenotype resembling emphysema, attributed to post-natal alveolarization arrest." (PMID 38540990, 2024). "Otherwise, several studies observed that SUMF1 (-/-) mice developed emphysema-like phenotype following an arrest of alveolarization, and even systemic inflammation and neurodegeneration." (PMID 37344788, 2023). "This emphysema-like phenotype was one of our first hints that perhaps SUMF1 may play a role in the development of COPD, which is hallmarked by the development of emphysema." (PMID 28464818, 2017). "Notably, a previous genome-wide association study identified an association between SUMF1 and prominent emphysema, although this association was not further investigated." (PMID 38540990, 2024). "It has been observed that mice lacking the sulfatase modifying factor (Sumf1) developed an emphysema-like phenotype." (PMID 28464818, 2017). "Among several SNPs that were identified in patients with prominent emphysema, one was in SUMF1, however, it was not studied futher." (PMID 28464818, 2017). "In addition to the emphysema-like phenotype, many cell and tissue types were found to have massive GAG accumulation in the Sumf1 −/− mice, but this has not yet been investigated in COPD." (PMID 28464818, 2017).
chronic obstructive pulmonary disease (3 papers, 2017 to 2024). A chronic and progressive lung disorder characterized by the loss of elasticity of the bronchial tree and the air sacs, destruction of the air sacs wall, thickening of the bronchial wall, and mucous accumulation in the bronchial tree. "Then, other studies showed that SUMF1 gene variation increased the risk of Chronic Obstructive Pulmonary Disease (COPD) by affecting the expression, activity and localization in lung fibroblasts." (PMID 37344788, 2023). "Certain variations in the splicing patterns of SUMF1 demonstrated diminished expression levels in sputum cells among individuals with chronic obstructive pulmonary disease (COPD) in comparison to those in the control group." (PMID 38540990, 2024). "However, it is unknown if SUMF1 may play a role in Chronic Obstructive Pulmonary Disease (COPD) in humans." (PMID 28464818, 2017).
glioma (3 papers, 2023 to 2024). A benign or malignant brain and spinal cord tumor that arises from glial cells (astrocytes, oligodendrocytes, ependymal cells). "This study aims to investigate the expression of SUMF1 and its associations with the prognosis, diagnosis, and immune microenvironment of patients with glioma." (PMID 38460946, 2024). "The overexpression of SUMF1 was positively correlated with poor prognosis and immune microenvironment and was an independent risk factor for poor prognosis in patients with glioma." (PMID 38460946, 2024). "To date, there is a lack of literature reports that have examined the association between sulfatase modifying factor 1 (SUMF1) and glioma." (PMID 38460946, 2024). "Moreover, SUMF1 overexpression was a notable risk factor independently associated with poor prognosis in patients with glioma." (PMID 38460946, 2024). "The nomograms and risk models associated with SUMF1 could predict the prognosis of patients with glioma." (PMID 38460946, 2024). "In this study, we found that the gene encoding SUMF1 was overexpressed in glioma tissues, particularly in those obtained from patients with IDH wild-type and non-codel subtype, aged >60 years, specific histological subtypes, and had poor OS, DSS, and PFI outcomes." (PMID 38460946, 2024). "SUMF1 overexpression was linked to the diagnosis of cancer, survival events, isocitrate dehydrogenase status, age, and histological subtype and was positively correlated with poor prognosis in patients with glioma." (PMID 38460946, 2024). "SUMF1-related nomograms and high-risk scores could predict the outcome of patients with glioma." (PMID 38460946, 2024). "However, SUMF1 has yet to be implicated in any other aspect of glioma." (PMID 38460946, 2024). "The survival analysis indicated a poorer prognosis for glioma patients with an overexpression of SUMF1." (PMID 38460946, 2024). "The levels of SUMF1 were significantly higher in glioma tissues in the TCGA and XNEA databases than in normal brain tissues." (PMID 38460946, 2024). "The analysis of the TCGA data revealed an AUC value of 0.728 for SUMF1 expression in glioma tissues." (PMID 38460946, 2024). "The CCK-8 showed a significant statistical difference in the absorbance values of U251 and U118 between 72 and 96 h, suggesting that inhibiting SUMF1 expression inhibits U251 and U118 cell growth in glioma." (PMID 38460946, 2024). "Analysis of the TCGA and XENA data revealed AUC values of 0.728 and 0.96, respectively, for SUMF1 overexpression in glioma." (PMID 38460946, 2024). "The Cox regression analysis revealed that several factors, including the overexpression of SUMF1, IDH status, 1p/19q codeletion, age, and histological subtype, contribute to the risk of poor OS, DSS, and cancer progression among glioma patients." (PMID 38460946, 2024). "A nomogram shows the relationship between the expression of the long non-coding RNAs and SUMF1 with respect to the PFI in patients with glioma." (PMID 38460946, 2024). "This previous finding informed our decision to analyze the relationship between SUMF1 and the glioma immune microenvironment." (PMID 38460946, 2024). "We further found that the expression of SUMF1, LINC01426, AC061992.2, CARD8-AS1, AC083855.2, AC027307.2, WAKMAR2, and LINC02636, were associated with adverse progression in patients with glioma." (PMID 38460946, 2024). "Furthermore, the time-dependent ROC analysis showed that the overexpression of SUMF1 had significant predictive value for patients with glioma at the 1-, 3-, and 5-year time points." (PMID 38460946, 2024). "Collecting more glioma tissues would have helped improve our data concerning SUMF1 expression." (PMID 38460946, 2024). "Additionally, the expression of LINC01426, AC061992.2, CARD8-AS1, AC083855.2, AC027307.2, WAKMAR2, LINC02636, and SUMF1 were correlated with adverse PFI in patients with glioma." (PMID 38460946, 2024).